RAD21 (RAD21 cohesin complex component)
Diseases named in the same sentence as RAD21 in open-access papers (continued):
Sharing a sentence is not in itself a finding about the gene and the disease.
ovarian carcinoma (13 papers, 2017 to 2025). A malignant neoplasm originating from the surface ovarian epithelium. "To investigate the potential mechanism underlying the promotion of ovarian cancer progression by RAD21, we investigated the signaling pathways related to RAD21 using Western blotting." (PMID 35860572, 2022). "Sehl et al17 reported that rs16888927, rs16888997, and rs16889040 in introns of Rad21 were associated with breast and ovarian cancer in 104 SNPs of 17 genes associated with double‐strand break repair." (PMID 29797792, 2018). "However, the mechanisms underlying the role of RAD21 in ovarian cancer and its effect on the response to PARP inhibitors remain unknown, warranting further exploration." (PMID 35860572, 2022). "Thus, RAD21 was upregulated in epithelial ovarian cancer and associated with a poor prognosis." (PMID 35860572, 2022). "However, the biological roles of RAD21 in ovarian cancer and their underlying mechanisms remain unclear." (PMID 35860572, 2022). "PUF60, Rad21, and LY6E are genes located on chromosome 8q24, an important locus associated with the progression of ovarian cancer and amplified region in around 14% of ovarian tumors." (PMID 39408764, 2024). "This was consistent with a recent study showing that the RAD21–YAP complex modulates immune response in ovarian cancer." (PMID 39659446, 2024). "We further used the Kaplan–Meier plotter to evaluate RAD21 in predicting the prognosis of ovarian cancer patients after chemotherapy." (PMID 35860572, 2022). "Based on the role of RAD21 in DNA damage repair, we first evaluated the effect of RAD21 on the sensitivity of ovarian cancer cells to standard chemotherapeutics." (PMID 35860572, 2022). "We elucidated RAD21 expression in ovarian cancer and its correlation with patient prognosis by using a large number of clinical specimens." (PMID 35860572, 2022). "We found that RAD21 was overexpressed in ovarian cancer and that patients with high RAD21 expression showed poor differentiation and poor overall survival." (PMID 35860572, 2022). "Univariate analysis suggested that high RAD21 expression, advanced FIGO stage, and lymph node metastasis were risk factors affecting the prognosis of patients with epithelial ovarian cancer." (PMID 35860572, 2022). "Results showed that ovarian cancer patients with high RAD21 expression had a poor prognosis after receiving platin." (PMID 35860572, 2022). "Here, we demonstrated that RAD21 was highly expressed in ovarian cancer, and its expression correlated with poor prognosis." (PMID 35860572, 2022). "To verify the relationship between RAD21 and the occurrence and development of ovarian cancer, we detected its expression level in clinical specimens and analyzed its correlation with pathological parameters." (PMID 35860572, 2022). "HPA database analysis also confirmed that RAD21 stained moderately or intensely in ovarian cancer tissues and was mainly localized in the nucleus." (PMID 35860572, 2022). "High RAD21 expression was correlated with poor differentiation and poor prognosis in patients with ovarian cancer." (PMID 35860572, 2022). "RAD21 promoted malignant biological behaviors of ovarian cancer cells by activating the Akt/mTOR signaling pathway and reduced the sensitivity of cancer cells to PARP inhibitors by affecting the DSB repair." (PMID 35860572, 2022). "An immunohistochemical assay was used to validate the expression of RAD21 in ovarian cancer and its correlation with prognosis." (PMID 35860572, 2022). "Relationship between RAD21 expression level in epithelial ovarian cancer and clinicopathological parameters." (PMID 35860572, 2022). "Collectively, these results indicated that RAD21 plays an important role in ovarian cancer progression." (PMID 35860572, 2022). "A total of 95 patients with epithelial ovarian cancer were divided into high (++/+++) and low (−/+) RAD21 expression groups." (PMID 35860572, 2022).
ovarian carcinoma (continued). "RAD21 played a key role in ovarian cancer progression and reduced sensitivity to PARP inhibitors through DNA damage repair." (PMID 35860572, 2022). "The immunohistochemical results showed that the Ki-67 staining of the RAD21 overexpression group was darker than that of the control group, indicating the pro-proliferative role of RAD21 in ovarian cancer." (PMID 35860572, 2022). "RAD21 can serve as a valuable prognostic marker for ovarian cancer and has the potential as a therapeutic target that can expand the utility of PARP inhibitors." (PMID 35860572, 2022). "When we treated RAD21-overexpressing ovarian cancer cells with PP242, the high ability of cell proliferation, migration, and invasion induced by RAD21 overexpression was reduced." (PMID 35860572, 2022). "We found that high expression of RAD21 increased the resistance of ovarian cancer cells to three PARP inhibitor types, and PARP inhibitor-induced cytotoxicity was augmented by inhibiting RAD21 expression." (PMID 35860572, 2022). "Moreover, PUF60, Rad21, and LY6E are located on chromosome 8q24, a locus often amplified and associated with the progression of ovarian cancer." (PMID 39408764, 2024). "Here, we explored the role of RAD21 in ovarian cancer in vitro and in vivo." (PMID 35860572, 2022). "Moreover, RAD21 knockdown increased the sensitivity of ovarian cancer cells to three kinds of PARP inhibitors by affecting DNA damage repair." (PMID 35860572, 2022). "Therefore, RAD21 plays a crucial role in ovarian cancer progression and is expected to become a prognostic factor and a therapeutic target for combination therapy with PARP inhibitors." (PMID 35860572, 2022). "Furthermore, PP242 reversed the RAD21 upregulation-induced resistance to PARP inhibitors in ovarian cancer cells." (PMID 35860572, 2022). "Furthermore, PP242 treatment attenuated the resistance of RAD21-overexpressing ovarian cancer cells to PARP inhibitors." (PMID 35860572, 2022). "Based on cell experiments, we explored the function of RAD21 in ovarian cancer cell lines." (PMID 35860572, 2022). "RAD21, by exerting a DSB repair function, enables rapid repair of DNA breaks caused by PARP inhibitor treatment, leading to cell survival and thus the resistance of ovarian cancer cells to PARP inhibitors." (PMID 35860572, 2022). "In summary, we revealed that RAD21 conferred a poor prognosis in ovarian cancer patients." (PMID 35860572, 2022). "Considering the role of the Akt/mTOR pathway in DNA damage repair, we hypothesize that RAD21 affects the ovarian cancer cell response to PARP inhibitors not only by mediating sister chromatid cohesion but also by activating the Akt/mTOR pathway." (PMID 35860572, 2022). "Thus, our findings highlight RAD21 as a prognostic factor and suggest the efficacy of silencing RAD21 in combination with PARP inhibitors to treat ovarian cancer." (PMID 35860572, 2022). "To explore whether RAD21 promoted malignant biological behaviors in ovarian cancer cells via the Akt/mTOR signaling pathway, we performed rescue experiments." (PMID 35860572, 2022). "Therefore, RAD21 likely promoted the progression of ovarian cancer by regulating the expression of MMP2 and MMP9, and its high expression predicted poor prognosis of ovarian cancer patients." (PMID 35860572, 2022).
ovarian carcinoma (continued). "Earlier investigations demonstrated that the amplification of RAD21 epigenetically restrains interferon signaling, thus promoting immune escape in ovarian cancer and having the potential to function as a molecular sign for immunotherapy regarding ovarian cancer." (PMID 40406120, 2025). "Therefore, RAD21 may reduce the sensitivity of ovarian cancer cells to PARP inhibitors by facilitating DSB repair." (PMID 35860572, 2022). "Furthermore, RAD21 overexpression increased ovarian cancer cell migration and invasion." (PMID 35860572, 2022). "To evaluate whether the knockdown of RAD21 sensitized ovarian cancer cells to PARP inhibitors by impairing DNA damage repair, we treated siRNA- or lentivirus-transfected cells with PARP inhibitors for 4 days at IC50 concentrations and quantified DSB formation based on the presence of γ-H2AX foci." (PMID 35860572, 2022). "Thus, RAD21 promoted ovarian cancer progression by activating the Akt/mTOR signaling pathway." (PMID 35860572, 2022). "Thus, RAD21 could serve as a novel prognostic ovarian cancer biomarker and a predictive target for the therapeutic efficacy of PARP inhibitors." (PMID 35860572, 2022). "However, the role of Rad21 in ovarian cancer development and progression has yet to be elucidated." (PMID 28831167, 2017). "We found that high RAD21 expression significantly reduced the accumulation of PARP inhibitor-induced γ-H2AX foci, suggesting that RAD21 affected the response of ovarian cancer cells to PARP inhibitors by participating in the DNA damage repair." (PMID 35860572, 2022). "To investigate the role of RAD21 in tumor immunity, we selected both murine ID8 ovarian cancer cells and mouse OVA-expressing B16 melanoma cells (B16-OVA), two well-established mouse synergic tumor models with a higher expression of Rad21." (PMID 36201246, 2022). "Therefore, to investigate the mechanisms by which RAD21 and CSE1L affect the efficacy of immunotherapy, we examined the correlations between various immune suppressive factors and RAD21/CSE1L in 14 ovarian cancer datasets." (PMID 40406120, 2025). "Previous studies have shown that RAD21 amplification epigenetically interacts with YAP/TEAD4 transcriptional co-repressors, recruiting the NuRD complex to inhibit interferon (IFN) signaling and promote immune evasion in ovarian cancer." (PMID 40406120, 2025). "Additionally, the gene expression of LY6E is related to the expression of RAD21 and PUF60, both genes are located at chromosome 8q24, a loci frequently amplified in ovarian cancer." (PMID 39408764, 2024). "Results showed that RAD21 knockdown increased the sensitivity of ovarian cancer cells to cisplatin but did not affect the effect of paclitaxel." (PMID 35860572, 2022). "However, the correlation between RAD21 and ovarian cancer prognosis has not been clarified." (PMID 35860572, 2022).
colon carcinoma (10 papers, 2013 to 2022). "In vivo experiments further verified that LINC00858 enhanced the tumorigenicity of colon cancer cells in vivo by regulating the RAD21/PCNP/STAT3/5 axis." (PMID 35468892, 2022). "Among those, RAD21 has been documented as highly expressed in multiple malignant tumors, including colon cancer, endometrial cancer, and prostate cancer, and is shown to promote cancer occurrence and development." (PMID 35468892, 2022). "In the current study, bioinformatic analysis in combination with RNA-FISH verified RAD21 as a target gene of LINC00858 in colon cancer." (PMID 35468892, 2022). "It indicated the promoting role of LINC00858 in colon cancer progression though activating PCNP-mediated STAT3/5 pathway by recruiting RAD21." (PMID 35468892, 2022). "RAD21, a key clamping component of the ring-like cohesin complex, is correlated with breast and colon cancer progression and is reported to alter the transcriptional activity of EMT-induced mesenchymal genes." (PMID 32370157, 2020). "In colon cancer, Deb et al6 conducted a retrospective study of 652 patients with colon cancer and found that Rad21 expression is related to disease progression, showing a positive correlation with chemotherapy in tumors harboring KRAS mutations and resistance." (PMID 29797792, 2018). "All in all, our results are consistent with the previous studies, and the function of RAD21 in colon cancer further indicates that GSTM2 may be involved in tumor formation as a suppressor." (PMID 36263204, 2022). "In order to study the effects of LINC00858 on the tumorigenicity of colon cancer cells by regulating the RAD21/PCNP/STAT3/5 axis in vivo, we injected SW480 cells transduced with adenovirus carrying oe-NC + sh-NC, oe-LINC00858 + sh-NC, oe-LINC00858 + sh-RAD21, oe-LINC00858 + sh-PCNP into nude mice." (PMID 35468892, 2022). "Next, we explored the involvement of the LINC00858/RAD21/PCNP axis in colon cancer pathogenesis." (PMID 35468892, 2022). "Furthermore, we demonstrated that LINC00858 could upregulate PCNP transcription in colon cancer by recruiting the transcription factor RAD21." (PMID 35468892, 2022). "Subsequently, we uncovered two potential reasons for the lower expression of GSTM2 in colon cancer tissues, including the deep deletion of GSTM2 on genome, and the up-regulation of RAD21 or SP1." (PMID 36263204, 2022). "The results showed that there were significantly negative expression correlations between the GSTM2 expression with the three transcription factors, which suggested CTCF, RAD21, SP1 as potential transcription factors of GSTM2 in colon cancer." (PMID 36263204, 2022). "As we knew that the transcription factors always had a correlated expression with their downstream genes, thus we used the GEPIA database to explore the expression correlation between GSTM2 and CTCF, RAD21, SP1 in colon cancer." (PMID 36263204, 2022). "Eventually, we identified RAD21 and SP1 as potential transcription factors of GSTM2 in colon cancer." (PMID 36263204, 2022). "RAD21 and SMC3 were found to be overexpressed in breast and prostate cancer and colon carcinoma, while SMC1A and RAD21 were found to be downregulated in acute myeloid leukemia and oral squamous cancer." (PMID 23426528, 2013). "In the current study, we set out to establish if LINC00858 affected the progression of colon cancer and revealed that LINC00858 could recruit RAD21 to regulate PCNP-mediated STAT3/5 signaling pathway, thereby promoting the development of colon cancer." (PMID 35468892, 2022). "Overall, the results obtained in the current study demonstrated that LINC00858 affects the progression of colon cancer and revealed that LINC00858 is able to recruit RAD21 to upregulate PCNP, which contributes to STAT3/5 signaling activation, thereby promoting the development of colon cancer." (PMID 35468892, 2022).
colon carcinoma (continued). "Therefore, of the three genes, the expression of RAD21 and SP1 in colon cancer matched the results of correlation analysis, so that RAD21 and SP1 might be the potential upstream transcription factors of GSTM2 in colon cancer." (PMID 36263204, 2022). "Consequently, the up-regulation of RAD21 and SP1 might be the second probable reason for the down-regulated expression of GSTM2 in colon cancer." (PMID 36263204, 2022). "As shown by Western blot assay, the overexpression or knockout of LINC00858 in SW480 and HCT166 cells did not affect the expression of RAD21, suggesting that LINC00858 did not directly regulate the expression of RAD21 to participate in the colon cancer development." (PMID 35468892, 2022).
acute myeloid leukemia (8 papers, 2013 to 2024). Acute myeloid leukemia (AML) is a group of neoplasms arising from precursor cells committed to the myeloid cell-line differentiation. "RAD21-inactivating heterozygous somatic mutations are a well-established correlate of various human cancers, such as acute myeloid leukemia (AML)." (PMID 35563565, 2022). "Mutations in the cohesin complex components (STAG2, RAD21, SMC1A, SMC3, and PDS5B) are recurrent genetic drivers in myelodysplastic neoplasm (MDS) and acute myeloid leukemia (AML)." (PMID 39033241, 2024). "The genetics of cohesinopathy provide evidence for RAD21, STAG2, SMC1A, and SMC3 as driver mutations in acute myeloid leukemia (AML), chronic myeloid leukemia (CML), and pre-leukemic states (myelodysplastic syndrome; MDS)." (PMID 35902807, 2022). "In some forms of acute myeloid leukemia (AML), the cumulative level of mutations in RAD21, SMC1a, SMC3, and STAG2 genes reaches 13%." (PMID 35353576, 2022). "In acute myeloid leukemia patients, EZH2 mutations frequently co-occurred with CEBPA (67%), ASXL1 (50%), TET2 and RAD21 mutations (33% each)." (PMID 33845873, 2021). "For example, somatic mutations in the eight genes that comprise the cohesin ring (SMC1A, SMC3, STAG1, STAG2, RAD21) and the cohesin-ring support genes (NIPBL, MAU2, WAPL, PDS5A, PDS5B) and CTCF are frequently found in many cancer types and are especially common in acute myeloid leukemia (AML)." (PMID 36171609, 2022).
leukemia (8 papers, 2016 to 2025). A malignant (clonal) hematologic disorder, involving hematopoietic stem cells and characterized by the presence of primitive or atypical myeloid or lymphoid cells in the bone marrow and the blood. "In HSCs, cohesin RAD21 depletion was found to reduce the PcG-associated repressive H3K27me3 mark and cause de-repression of PcG target genes, particularly at leukemia-associated HoxA7 and HoxA9, consequently enhancing self-renewal." (PMID 34202641, 2021). "Understanding the influence of RAD21 germline variants may offer new treatment options such as their potential sensitivity to PARPP inhibitors which are already included in clinical trials in leukemias with somatically mutated cohesin." (PMID 35563565, 2022). "To confirm a correlation between germline RAD21 p.P298S/A and pediatric leukemia, we analyzed an additional unpublished pediatric cancer cohort of 150 children with relapsed ALL (Italian IntReALL standard risk study; R-ALL) for RAD21 p.P298S/A." (PMID 35563565, 2022). "Furthermore, two cases with somatic truncating mutations in RAD21 were recently identified in a study of pediatric precursor B-cell ALL (BCP-ALL) with very early relapse and somatic cohesin mutations have been reported in pediatric high hyperdiploid leukemia." (PMID 35563565, 2022). "Increased sensitivity to Wnt stimulation was also observed in cohesin STAG2 mutant leukemia cells, HCT116 colorectal cells that overexpress mutant SMC1A and in rad21 and stag2b mutant zebrafish models." (PMID 34202641, 2021). "For example, while selectively disrupting chromatin loops in leukemia cells using STAG2 inhibitors, strategies could be developed to dynamically control RAD21 cleavage by modulating separase activity to enhance HSC regeneration." (PMID 40642059, 2025). "In a fourth cohort including 114 children and adolescents with therapy refractory leukemia and lymphoma (INFORM), no germline indels or missense variants affecting RAD21 were identified, suggesting no enrichment in the relapsed or therapy refractory patients." (PMID 35563565, 2022).